IL1A (interleukin 1 alpha)
Diseases named in the same sentence as IL1A in open-access papers (continued):
Sharing a sentence is not in itself a finding about the gene and the disease.
metastatic colorectal cancer (3 papers, 2017 to 2025). "Another monoclonal neutralizing antibody targeting IL-1α, Bermekimab, was used in a randomized, placebo-controlled study to evaluate the efficacy of the treatment in 333 patients with advanced, metastatic colorectal cancer." (PMID 38382577, 2024). "TASKIN is the first early-phase clinical trial testing the hypothesis of tolerance and efficacy of the association between trifluridine/tipiracil + bevacizumab and anti-IL-1α mAb immunotherapy for multi-treatment metastatic colorectal cancer (mCRC)." (PMID 39820336, 2025). "This study represents the first clinical results for the usage of XB2001, an IL-1α-targeting monoclonal antibody (mAb), in humans, addressing the critical need for effective treatments in metastatic colorectal cancer (mCRC), particularly in chemo-resistant cases." (PMID 39820336, 2025). "XilonixTM blocks the IL-1α produced by the body in response to tumor growth and it is being tested in an FDA fast tracked, pivotal phase 3 study for the treatment of metastatic colorectal cancer (NCT02138422, NCT01767857)." (PMID 28219375, 2017). "XB2001, a fully human monoclonal antibody neutralizing IL-1α, was evaluated for safety and preliminary efficacy with trifluridine/tipiracil (FTD/TPI) and bevacizumab in metastatic colorectal cancer patients previously treated with oxaliplatin- and irinotecan-based chemotherapies." (PMID 39820336, 2025).
myocardial ischemia (3 papers, 2017 to 2023). A disorder of cardiac function caused by insufficient blood flow to the muscle tissue of the heart. "Interestingly, levels of IL-1α only differentiate Group 2 patients from Group 1 during and immediately following surgery, with elevations of IL-1α potentially representing a compensatory response to myocardial ischemia." (PMID 33670210, 2021). "We previously reported that IL-1α is released as a DAMP from necrotic cardiomyocytes and triggers inflammatory responses in an acute model of myocardial ischemia and reperfusion." (PMID 36899010, 2023).
oral lichen planus (3 papers, 2012 to 2021). Oral lichen planus is a chronic inflammatory oral condition of unknown aetiology characterized by T-cell-mediated chronic immune response and abnormal epithelial keratinization cycle. "We decided to evaluate the panel of four proinflammatory, NF-kappaB dependent cytokines (IL-1α, IL-6, IL-8, and TNF-α) not only in saliva, but also in tissue specimens of OSCCs and OPMDs such as oral leukoplakia and oral lichen planus." (PMID 32245251, 2020). "The present study also confirmed the expression of IL-1α, IL-6, IL-8, and TNF-α in oral leukoplakia and oral lichen planus specimens." (PMID 32245251, 2020).
oral mucositis (3 papers, 2022 to 2025). Inflammation of the mucous membranes of any of the structures in the mouth. "Both Il1a and Illb transcripts were upregulated in the Il17ra−/− HNI + OPC mice compared to WT and may account for the increased neutrophil influx in the tongue tissue, which is similar to the role of IL-1α and IL-1β at the peak of damage during oral mucositis caused by HNI-only in Il17ra−/− mice." (PMID 35628751, 2022). "For instance, in radiation-induced oral mucositis, the miR-200 family alleviates inflammation by suppressing cytokines, such as TGF-β, TNF-α and IL-1α." (PMID 40909958, 2025).
osteosarcoma (3 papers, 2013 to 2025). A usually aggressive malignant bone-forming mesenchymal neoplasm, predominantly affecting adolescents and young adults. "Using Human Osteosarcoma Cells, it has also been found that 15 inflammatory cytokines, particularly embracing IL-1α, increased when the cells were treated with cold atmospheric plasma." (PMID 34863132, 2021). "The production of IL-1α, a pro-inflammatory cytokine with stimulatory effects on osteoclastogenesis, is suppressed by Osx in osteosarcoma cells." (PMID 23922826, 2013). "A more recent study using preclinical models of osteosarcoma showed that pulmonary metastasis is initiated by a subpopulation of disseminated tumor cells that produce cytokines such as IL-6 and CXCL8 in response to lung-epithelium-derived IL-1α." (PMID 41008853, 2025).
pancreatic adenocarcinoma (3 papers, 2013 to 2016). "We aimed at exploring TGFβ and IL-1α signaling and cross-talk in the stellate cell cancer cell interactions regulating pancreatic adenocarcinoma cell migration." (PMID 27473228, 2016). "Pancreatic stellate cell responses to IL-1α or to IL-1α-expressing pancreatic adenocarcinoma cells (BxPC-3) were characterized by their ability to stimulate migration of cancer cells in a 2D migration model." (PMID 27473228, 2016). "The inflammation is a hallmark for pancreatic adenocarcinoma (PDAC) and is to high extent driven by IL-1α." (PMID 23951028, 2013).
pancreatic ductal adenocarcinoma (3 papers, 2013 to 2019). An infiltrating adenocarcinoma that arises from the epithelial cells of the pancreas. "A previous study suggested that IL-1α expression in pancreatic ductal adenocarcinoma could be regulated by p38MAPK." (PMID 31288851, 2019). "In addition, IL-1α overexpression is correlated with Kras mutation and NF-κB activation in human pancreatic ductal adenocarcinoma specimens and poor survival in pancreatic ductal adenocarcinoma patients, suggesting that NF-κB activation by IL-1α/IL-1R signal is important to tumor progression." (PMID 24924428, 2014).
pertussis (3 papers, 2016 to 2025). A contagious bacterial respiratory infection caused by Bordetella pertussis. "Our current in vivo study demonstrated that immunization with an OMV-based pertussis vaccine (omvPV) in comparison to wPV elicited reduced concentrations of serum pro-inflammatory cytokines (IL-1α, IL-1β, and IL-6), chemokines (CXCL1 and CXCL10), and G-CSF." (PMID 27905535, 2016).
prostate tumor (3 papers, 2018 to 2025). "Exogenous IL1A reinstated the capacity of senescent mouse fibroblasts to enhance prostate tumor growth through MTOR inhibition." (PMID 40612864, 2025). "Reduction of IL-1α expression by prostate tumor cells with shRNA (short hairpin RNA) also significantly inhibited tumor growth." (PMID 29502208, 2018). "Further analysis showed that IL-1α inhibition led to decreased angiogenesis within tumors, suggesting that IL-1α promotes prostate tumor progression, potentially through augmentation of angiogenesis." (PMID 29502208, 2018). "Both in vitro and in vivo blockade of the IL-1α pathway with its natural antagonist IL-1Ra abolished expression of downstream targets of IL-1α and significantly decreased prostate tumor growth and angiogenesis." (PMID 29502208, 2018).
psychosis (3 papers, 2013 to 2026). "In ASD cases, there were significantly increased levels of inflammatory cytokines IL-1α, IL-8, G-CSF, M-CSF and GROa compared to both controls and psychotic disorder." (PMID 42239763, 2026). "Gene expression analyses conducted only in those cytokines that were different in the serum (IL-1α, IL-1β, IL-6, IL-8 and TNF-α) revealed significantly increased mRNA levels of IL-1α (d = 0.6), IL-6 (d = 0.7) and TNF-α (d = 1.6) in first-episode psychosis patients when compared with controls." (PMID 22749891, 2013).
pustular psoriasis (3 papers, 2021 to 2024). "Anakinra, a recombinant IL-1 receptor antagonist (IL-1Ra) inhibits both IL-1α and IL-β and has shown efficacy in pustular psoriasis and deficiency of IL-1 receptor antagonist (DIRA) variant." (PMID 35265634, 2022). "We selected anakinra as our preferred IL‐1 blocker because, uniquely, it blocks both IL‐1α and IL‐1β, it has a rapid onset of action and established safety profile (> 70 000 patient‐years exposure), there was early evidence of benefit in pustular psoriasis and has the lowest drug acquisition costs." (PMID 34411292, 2021). "Furthermore, skin explants of pustular psoriasis cultured with a neutralizing anti-IL-26 mAb but not anti-IL-17A mAb completely inhibited the expression of CXCL1, CXCL8, and IL1A, confirming the specific role of IL-26 as a driver of pathogenic autoinflammation circuits." (PMID 38448036, 2024).
sarcopenia (3 papers, 2022 to 2026). Progressive decline in muscle mass due to aging which results in decreased functional capacity of muscles. "In murine models of sarcopenia, coffee intake increased muscle mass, accelerated the regeneration of injured muscles and decreased some proinflammatory markers such as the interleukins IL-1α, IL-6, and tumor necrosis factor alpha (TNF-α)." (PMID 39275165, 2024). "Increased levels of IL-1α, IL17A and CXCL5 have been linked to sarcopenia and cardiotoxicity." (PMID 36611902, 2022).
triple-negative breast carcinoma (3 papers, 2021 to 2024). An invasive breast carcinoma which is negative for expression of estrogen receptor (ER), progesterone receptor (PR), and human epidermal growth factor receptor 2 (HER2). "Here, we focused on the pharmacological effect of Entelon® (ETL) on the tumorigenesis of triple-negative breast cancer (TNBC) cells by IL1-alpha (IL1A)." (PMID 34203721, 2021).
urinary tract infection (3 papers, 2007 to 2016). "Patients with a urinary tract infection had decreased levels of IFN-α2 in the prostate while having increased levels of IL-1α and IL-8 compared to patients with a negative urine culture." (PMID 26993768, 2016).
vaginal infection (3 papers, 2020 to 2024). "This modulation is associated with a significant reduction in the secretion of three key pro-inflammatory cytokines, IL-6, IL-1α, and IL-1β, which are typically upregulated during C. albicans vaginal infection and contribute to the inflammatory milieu." (PMID 39770658, 2024). "The second of these was assessed with a multi-analyte flow assay kit to determine the levels of IL-6, TNF-α, IL-1β, IL-10, IL-1α, IL-17a, MCP-1, and IFN-γ in the supernatant of cervical tissue homogenate of GrpE-immunized mice and control groups after vaginal infection." (PMID 32849509, 2020).
varicocele (3 papers, 2017 to 2023). A condition characterized by the dilated tortuous veins of the spermatic cord with a marked left-sided predominance. "According to the previous study, proinflammatory cytokines such as IL-1α and IL-1b increased 11 and 13 wk after varicocele induction, respectively." (PMID 37727396, 2023). "In varicocele,it has been also suggested that expression of IL-1α and IL-1β, as proinflammatory cytokines, wereincreased." (PMID 28868836, 2017).
ZIKV infection (3 papers, 2021 to 2025). "Additionally, genes encoding cytokines and chemokines, including IL-1α, Il-1β, Cxcr4, and Cxcl10, were significantly upregulated in response to ZIKV infection, suggesting the presence of neuroinflammation." (PMID 39273400, 2024). "ZIKV infection increases the levels of a series of cytokines (IL-1α, IL-6, IL-9, IL-10, IL-12p70, and IFN-γ) and chemokines (CCL2, CCL3, CCL4, CCL5, CCL11, and CXCL1) in mouse brain." (PMID 34399779, 2021). "In ZIKV infection, elevated IL-1A (as we observed) may similarly drive blood–brain barrier permeability and enhance glial activation, thereby promoting neuroinflammation and facilitating viral entry into the central nervous system via disruption of tight junctions." (PMID 40927453, 2025). "Our results also point to the potential of boosting the IL-1A and CXCL8 pathways as antiviral strategies in ZIKV infection." (PMID 40927453, 2025).
Abdominal obesity (2 papers, 2022 to 2024). Excessive fat around the stomach and abdomen. "Individuals with abdominal obesity often exhibit high levels ofproinflammatory cytokines (tumor necrosis factor-α (TNF-α), interleukin-1α (IL-1α), interleukin-1β (IL-1β), interleukin-6 (IL-6)and interleukin-8 (IL-8)), which can be considered significant prognostic indicators of CVD risk." (PMID 39076338, 2024).
acute lymphoblastic leukemia (2 papers, 2014 to 2022). Leukemia with an acute onset, characterized by the presence of lymphoblasts in the bone marrow and the peripheral blood. "For example, in acute lymphocytic leukemia T cells, overexpression of the IL1A nuclear propeptide has been demonstrated to promote proliferation and reduce apoptosis, by NFkB and SP1 up-regulation." (PMID 34997006, 2022). "In humans, interleukin-1 alpha has been related with orchitis, relapse of acute lymphoblastic leukemia in the testis, and infertility disorders in men." (PMID 24895614, 2014).
adenovirus infection (2 papers, 2016 to 2019). "Il1a encodes IL-1α, a cytokine that has already been implicated in the response to adenovirus infection." (PMID 30787914, 2019). "Macrophages are the first line of cellular defense against invading pathogens and the IL-1α-IL-1RI pathway has been identified as a key driver of inflammatory cytokine and chemokine activation after adenovirus infection." (PMID 27583193, 2016).
alcoholic cirrhosis (2 papers, 2015 to 2024). "In the study, concentrations of HGF, IL-1α, and IL-6 were analyzed in patients with alcoholic liver cirrhosis classified according to the Child-Pugh scoring system." (PMID 26448742, 2015). "The aim of the study was to evaluate concentrations of HGF protein and proinflammatory cytokines IL-1α and IL-6 in serum of patients with different stages of alcoholic liver cirrhosis." (PMID 26448742, 2015). "Concentrations of HGF, IL-1α, and IL-6 increase with severity of alcoholic liver cirrhosis, and the concentration of HGF increases with an increase in proinflammatory cytokines concentration." (PMID 26448742, 2015). "According to our best knowledge, relationship between serum concentrations of HGF and serum concentrations of the proinflammatory cytokines (Il-1α, Il-6) in patients with alcoholic cirrhosis has not been described yet." (PMID 26448742, 2015).
allergic contact dermatitis (2 papers, 2014 to 2016). An inflammatory skin condition caused by an immune response to direct contact between the skin and an allergen. "In the initiation of allergic contact dermatitis, for example, IL-1β but not IL-1α appears to be important, whereas in irritant contact dermatitis IL-1α appears to play a more important role." (PMID 25371210, 2014).
allergic rhinitis (2 papers, 2022 to 2024). Inflammation of the nasal mucous membranes caused by an IgE-mediated response to external allergens. "IL-1α production was shown to be associated with antigen-induced late nasal response in patients with allergic rhinitis." (PMID 38398010, 2024). "It was stated that differences in genotype distribution “was mainly due to an increased number of IL1A allele G homozygotes and IL1RN allele 2 homozygotes in allergic rhinitis”." (PMID 36518750, 2022).
alopecia areata (2 papers, 2010 to 2024). Loss of scalp and body hair involving microscopically inflammatory patchy areas. "In human scalp areas affected by alopecia areata, an excessive expression of IL-1β is detected particularly at the early stages of the disease, while susceptibility to the disease and severity are determined by polymorphisms of the IL-1-receptor antagonist and IL-1a." (PMID 20300578, 2010). "IL-1α is a direct growth inhibitory agent in hair follicles and plays an important role in the pathogenesis of alopecia areata." (PMID 39768634, 2024).
apical periodontitis (2 papers, 2024). "Cytokines such as IL-1α, IL-1β, IL-6, IL-8, and IL-12p40 play significant roles in the development of apical periodontitis." (PMID 39723289, 2024). "Multiple studies have investigated the polymorphisms of various ILs, including IL-1α, IL-1β, IL-6, TNF-α, IL-8, IL-10, and IL-12, and their association with the occurrence of apical periodontitis." (PMID 39723289, 2024). "IL-1α and IL-1β, released by macrophages, lymphocytes, and dendritic cells, are two pro-inflammatory cytokines that play a significant role in developing and progressing apical periodontitis by activating osteoclasts and promoting bone resorption." (PMID 38956025, 2024).
arteriosclerosis (2 papers, 2015 to 2020). A vascular disorder characterized by thickening and hardening of the walls of the arteries. "Although IL-1α released from damaged ECs drives immune responses that cause arteriosclerosis and graft failure, what controls IL-1α activity in ECs is unknown." (PMID 26324711, 2015). "In conclusion, our data show that although EC-derived IL-1α is key in driving graft arteriosclerosis, it is inactive in unstimulated ECs due to binding to IL-1R2." (PMID 26324711, 2015). "IL-1α released from damaged ECs drives the T helper 17 cell (Th17) responses that induce vessel arteriosclerosis and subsequent allograft rejection, suggesting that ECs must be able to activate pro-IL-1α." (PMID 26324711, 2015). "In addition, these data suggest that inhibition of inflammasomes, caspase-1, calpain, or IL-1α are potential therapeutic candidates to prevent arteriosclerosis and allograft rejection." (PMID 26324711, 2015). "Within this milieu of IL-1α- and IL-1-induced cytokines CD4 memory T cells will be pushed toward the Th17 lineage with production of IL-17 and instigate arteriosclerosis and graft rejection." (PMID 26324711, 2015). "KCASP1Tg mice continually discharge IL-1α/β and other cytokines from the eczematous skin lesions, resulting in the non-aterotic aortic sclerosis, and this arteriosclerosis was perticially ameliorated by the combination treatment with anti-IL-1α/β neutralizing antibodies." (PMID 32825298, 2020).
astrocytoma (2 papers, 2020 to 2023). "In astrocytoma cells, IL-1α contributes to the transcription and activation of IL-8 and IL-6, thereby inducing chronic inflammation." (PMID 33235296, 2020). "Despite the strong signatures of IL-1 signaling in the recombinant astrocytoma and in human (M2) macrophages, we were unable to detect P2Y11-induced IL-1 (IL-1α and IL-1ß) in the supernatants of these cells." (PMID 37016172, 2023).
autism spectrum disorder (2 papers, 2021 to 2023). A spectrum of developmental disorders that includes autism, and Asperger syndrome. "Examination of cytokines and chemokines in archived maternal serum samples in the Early Markers for Autism (EMA) study demonstrated that elevated levels of GM-CSF, interferon-γ, IL-1α, and IL-6 were associated with autism spectrum disorder with intellectual disability." (PMID 37950045, 2023).
auto-inflammatory syndrome (2 papers, 2018 to 2019). "In our model, serum IL-1β levels increased in hIL-1α cTg mice, suggesting that IL-1α stimulates inflammasome activation, and our model recapitulates, at least in part, human auto-inflammatory syndrome." (PMID 30361689, 2018).
bacteremia (2 papers, 2013 to 2025). "In the present study, 3 cytokines (TNF-α, IL-1α, and KC) emerged as biomarkers for fatal outcome of S. aureus bacteremia." (PMID 23520553, 2013). "According to the binary logistic regression analysis, TNF-α, IL-1α, KC, G-CSF, IL-6, IL-12p70, IP-10, and MIP-1α are indicative for presence of S. aureus bacteremia in mice, while TNF-α, IL-1α, and KC were also potential biomarkers for fatal outcome of this infection." (PMID 23520553, 2013).
binge eating disorder (2 papers, 2019 to 2021). Recurrent episodes of over-eating. "IL-1α, IL-10, EGF, and IFN-γ were altered individuals with anorexia nervosa (AN) and binge eating disorder (BED)." (PMID 31450770, 2019).